ICAM1 (intercellular adhesion molecule 1)
Diseases named in the same sentence as ICAM1 in open-access papers (continued):
Sharing a sentence is not in itself a finding about the gene and the disease.
infection (continued). "Endothelial cell adhesion molecule (ICAM-1, VCAM, E- and P-selectin) expression in brain tissue on day 6 of infection was assessed in both groups by western blot." (PMID 21649904, 2011). "Since contrary data exist about the role of ICAM-1 and VCAM-1 in PMN adhesion and transmigration we were interested in their role on PCPECs after infection with S. suis." (PMID 21592385, 2011). "At 24 h post-infection, there is still an excellent correlation between both virus stocks, although the modulation induced by NL4-3 wt is overall greater than for ICAM-1+ viruses." (PMID 19146679, 2009). "The active contribution of LFA-1/ICAM-1 interaction to HIV spread has been described during free virus infection of CD4 T cells and infection mediated by DC." (PMID 18377648, 2008). "In arthritic joints of SCID mice infected with B. burgdorferi, Schaible and coworkers observed the appearance of PNAd only late during infection following early upregulation of other adhesion molecules such as P-selectin, VCAM-1 and ICAM-1." (PMID 16772045, 2006). "ICAM-1 is upregulated in epithelial cells of large and small airways of chronic airflow limitation patients, crucial for the infection of around 60% of human rhinoviruses, and non-typeable Haemophilus influenzae." (PMID 41440381, 2025). "In contrast, RV14 infections resulted in non-significant increases in ICAM-1 expression, with fold changes of only 1.32 ± 1.24." (PMID 40520162, 2025). "ICAM-1 concentrations were elevated in unvaccinated animals on days 3, 7, and 9 following infection, but did not change in vaccinated dogs." (PMID 41159782, 2025). "Consequently, we delved deeper into the interaction between endogenous ICAM-1 and phosphorylated Src under EMCV infection conditions." (PMID 40631914, 2025). "Second, the C5a/C5aR signalling upregulates the CD11b expression of neutrophils and promotes Mac-1 (CD11b/CD18) binding to Intercellular Adhesion Molecule-1 (ICAM-1) of vascular endothelial cells, which mediates trans-endothelial migration of neutrophils to the infection loci." (PMID 41017910, 2025). "Based on the higher affinity of S. pneumoniae to PAFr, compared than ICAM-1 (as observed in blocking experiments) or Hib, this could serve as an explanation for preferred binding of the prior during RV14 infections." (PMID 40520162, 2025). "Of note, intestinal Mφs and DCs downregulated most of these proteins at this timepoint in the gut following infection with the exception of ICAM1, and no genotype-dependent differences were identified (data not shown)." (PMID 40404738, 2025). "Additionally, it suppresses the expression of MHC-II molecules and adhesion molecules (ICAM-1 and VCAM-1), which impairs antigen delivery, hinders the immune system’s clearance of S. suis, and facilitates the establishment of a persistent infection." (PMID 41304154, 2025). "Conversely, scFv-ICAM1 chimera for foot-and-mouth disease virus (FMDV) resulted in successful uptake and infection into non-FMDV-susceptible cells." (PMID 40207931, 2025). "Both cell types exhibited increased ICAM-1 expression, even without direct infection, indicating that contact with T. gondii triggers cellular responses." (PMID 40141288, 2025). "Furthermore, IL-1β enhances the expression of adhesion molecules, including intercellular adhesion molecule-1 (ICAM-1) and vascular cell adhesion molecule-1 (VCAM-1), which facilitate immune cell recruitment to the site of infection or injury." (PMID 40155968, 2025). "The non-virus containing 0.1% DMSO infection medium for dissolving the drug did not change and did not affect ICAM-1 baseline expression." (PMID 39598462, 2024). "Consequently, ICAM-1 is considered a pivotal factor in CVA21 entry, uncoating, and replication under normal infection conditions." (PMID 39539548, 2024). "We hypothesize that PAFR and ICAM–1 expression is upregulated in IPF, which act as adhesion sites for bacteria/viruses, increasing the vulnerability to infection in IPF patients." (PMID 38610892, 2024).
infection (continued). "Also, infection of the THP-1 monocytes upregulates integrin LFA-1 and MAC-1, the ligand of ICAM-1, and VLA-4, the ligand of VCAM-1, which promotes the transmigration of monocytes across the BBB." (PMID 39840010, 2024). "In M1 pro-inflammatory-like macrophages, m6A was found in transcripts that are highly expressed and translated during macrophage response to infection including TLR4 (Toll-Like Receptor 4), ICAM1 (Intracellular Adhesion Molecule 1) and YAP1 (Yes-associated protein 1)." (PMID 38780787, 2024). "In the cell models we used (hMDMs and HeLa OHIO), no modulation in ICAM-1 expression was observed upon HRV16 infection." (PMID 39324790, 2024). "(B.2.1) Endothelial cells stimulated by IL-37 expression through the secretion of inflammatory mediators, including IL-1β, TNF-α, and IFN-γ, which positively induce adhesion molecules like E-selectin, ICAM-1, VCAM- 1, and VLA-4 that allow immune cells to go to the infection site." (PMID 39308868, 2024). "Our results displayed some proteins (IRG1, GBP5, PDL1, and ICAM1) correlated in all the conditions forming a unique section, in combination with other proteins in each specific condition, such as RSAD2, presented only in the Y infections." (PMID 39000601, 2024). "Post-infection, excessive production of inflammatory mediators such as IL-1β, IL-6, IL-8, TNF-α, MCP-1, and IP-10, as well as the presence of endothelial inflammation markers (IL-6, TNF-α, ICAM-1) in lung tissues, have also been reported." (PMID 38600563, 2024). "Furthermore, genes involved in immunity and infection [e.g., chemokine ligand 19 (ccl19), dedicator of cytokinesis 8 (DOCK8), and intercellular adhesion molecule-1 (ICAM-1)] were also significantly dysregulated." (PMID 36984847, 2023). "Endothelial cells respond to C. albicans infection by expressing adhesion molecules, such as intercellular adhesion molecule-1 (ICAM-1) and vascular cell adhesion molecule-1 (VCAM-1), which promote the binding and migration of leukocytes to the site of infection." (PMID 37511508, 2023). "Notably, our results showed an upregulated transcriptional expression of cytokines (IL-1β, IL-6 and TNF-α), adhesion molecules (VCAM-1, ICAM-1) and chemokines (CXCL1 and CXCL2) after infection in both brain cortex and hippocampus." (PMID 36778380, 2023). "Additionally, an in vivo study on Miana demonstrated an anti-inflammatory impact following infection of bacteria as well as a reduction in the levels of IL37, VEGF, HIF-1, and Intracellular Adhesion Molecule-1 (ICAM-1)." (PMID 38058621, 2023). "In this case, A. lancea and Prabchopoothaweep remedy alone downregulated the production of ICAM-1, VCAM-1, and CD36 on day 13 post-infection, while the expression of ICAM-1, VCAM-1, and CD36 was significantly lower than that in the Art-AL and Art-PT combination treatment groups." (PMID 37730604, 2023). "In A549 cells infected with RSV∆sG, increased mRNA and protein levels of intercellular adhesion molecule-1 (ICAM-1), IL-8 and Regulated upon Activation, Normal T Cell Expressed and Presumably Secreted (RANTES) were observed, compared to infection with wild-type RSV." (PMID 35216012, 2022). "In terms of ICAM1 expression, intravascular cytotoxic T cells (CD8+) were increased in 1/148 infections (two-way ANOVA, p-value = 0.0120) and extravascular ICAM1+ B cells were increased in IL3000 infections (two-way ANOVA, p-value < 0.0001)." (PMID 35787830, 2022). "In addition to the canonical roles of endothelial ICAM-1, this study identifies a previously unappreciated role for leukocyte ICAM-1 in infection-related TEM." (PMID 35990682, 2022). "Representative images obtained by intravital microscopy, of parasite sequestration in the brain vasculature upon treatment with α-ICAM1 antibody or its isotype control with and without perfusion, at day 6 post-infection." (PMID 35787830, 2022).
infection (continued). "Surprisingly, double ICAM-1 and ICAM-2 knock out mice (herein ICAM-1/2-/- mice) infected with a lab adapted H1N1 influenza A virus fully recovered from infection, elicited potent humoral immunity, and generated normal long lasting anti-viral CD8+ T cell memory." (PMID 36895258, 2022). "During IL3000 infections, we did not observe increased ICAM1 expression in remaining organs (right)." (PMID 35787830, 2022). "The infection process in these DCs does not generate significant changes in the levels of the adhesion molecule CD38 or intercellular adhesion molecule-1 (ICAM-1), and the expression of the CD83 costimulatory molecule, as compared to HSV-1-infected iDCs." (PMID 34895058, 2021). "Interestingly, bafilomycin A1 repressed the ICAM-1 production and decreased the viral titers of RV14 before and after its confirmed infection." (PMID 33937285, 2021). "Moreover, ICAM-1 expression by brain CD31+ cells (putative endothelial cells), was also comparable in infected PMCA4−/− and WT mice on day 7 of infection." (PMID 34215257, 2021). "The lack of cell death further corroborates the absence of productive infection observed in ICAM-1(-) cells treated with the virus." (PMID 34503272, 2021). "TNFα pre‐treatment of HMVEC‐L did not lead to further increase in nucleocapsid protein‐positive cells compared to untreated HMVEC‐L after infection with 2 × 106 PFUs of SARS‐CoV‐2, despite increased ICAM‐1 intensity levels demonstrating TNFα‐driven HMVEC‐L cell activation." (PMID 34721846, 2021). "Following rAd infection, mouse bone marrow-derived immature DCs were shown to upregulate the expression of MHC class I and II antigens, costimulatory molecules (CD40, CD80, and CD86), and the adhesion molecule ICAM-1." (PMID 34639132, 2021). "Intercellular adhesion molecule-1 (ICAM-1), a type 1 glycoprotein in the immunoglobulin superfamily, promotes the entry and infection of RSV in human epithelial cells by binding to RSV F protein, which is important for viral replication and infection." (PMID 34671221, 2021). "HRV-16 (108 copies), which uses ICAM-1 as its receptor, led to measurable levels of IL-17C release from all 4 donors at 48 h post infection, but these were not significantly increased compared to control because of the wide range of individual values." (PMID 32232015, 2020). "As we have previously reported, infection with B. abortus in the absence of platelets induced a slight activation of HBMECs, measured as the upregulation of surface ICAM-1." (PMID 32867217, 2020). "Regardless of the duration of infection, the majority of internalized P. gingivalis (79–88%) was found in ICAM-1 positive vesicles." (PMID 32341760, 2020). "Keratocytes are also known to upregulate adhesion molecules following infection, including ICAM-1/CD54, which are hypothesized to further promote the extravasation of leukocytes into the cornea." (PMID 31540200, 2019). "Subsequently, we used RNA-sequencing to explore the potential host factors involved in this infection process, and herein, we laid emphasis on two host molecules, PDGF-BB and ICAM-1, which were significantly induced by the challenge of meningitic E. coli PCN033." (PMID 31092253, 2019). "Trafficking of neutrophils and monocytes through the endothelium towards the site of infection is then facilitated by crawling via macrophage-antigen-1 (Mac-1/CD11b) expressed on monocytes and the intercellular adhesion molecule-1 (ICAM-1/CD54) expressed on endothelial cells." (PMID 30791481, 2019). "In addition corneal epithelial cell-derived interleukin-1 alpha (IL-1α) promotes the expression of ICAM-1 and VCAM-1 on endothelial cells following infection." (PMID 31540200, 2019).
infection (continued). "Meanwhile, the infection-induced upregulation of ICAM-1 in endothelial cells was completely abolished, without any ICAM-1 expression in the knockout cells." (PMID 31092253, 2019). "In diabetic rats (DATCC), infection resulted in the expression of ICAM-1 and P-selectin, but not of PECAM-1, and insulin treatment did not alter this pattern." (PMID 30705678, 2018). "Similar, also mice with T. cruzi infection express significantly more VCAM-1 and ICAM-1 on their cardiac endothelium compared to mice without infection." (PMID 29536322, 2018). "Furthermore, OPN did not appear to contribute to BBB compromise directly in our mouse model, while Opn−/− mice had reduced gene expression of Icam-1 and TNF-α levels early in the course of infection (D2 p.i.)." (PMID 28680095, 2017). "In addition, K5, which is expressed very early upon infection and at a low level during latency, can down-regulate expression of ICAM-1 (CD54) and B7-2 (CD86), which are ligands for natural killer (NK) cell mediated cytotoxicity." (PMID 28881567, 2017). "Parasite tissue sequestration and the development of acute stage pathology in P. chabaudi infections of mice lacking CD36 or ICAM-1, their respective wild type controls, and in infections with mutant P. chabaudi parasites lacking the smac gene were compared." (PMID 28468674, 2017). "Although clearly the lack of ICAM-1 modulates the infection in vivo, the capacity of P. chabaudi iRBC to bind to cell lines expressing different recombinant receptors in vitro would give more direct evidence of the relevant host/parasite interactions." (PMID 28468674, 2017). "Phenotypically, U937 cells aggregated after infection with H. pylori in a T4SS-dependent manner by the upregulation and recruitment of ICAM-1 (intercellular adhesion molecule 1) to the surface of U937 cells, indicating that a functional T4SS and possibly CagA are implicated in this process." (PMID 27382024, 2016). "Second, pretreatment of HTE and HNE cells with EM900 did not reduce ICAM-1 expression prior to RV14 infection." (PMID 26462747, 2015). "Pretreatment of the cells with EM900 did not reduce baseline ICAM-1 mRNA expression by the HTE or HNE cells compared with the levels detected in the cells pretreated with vehicle prior to RV14 infection." (PMID 26462747, 2015). "Treatment with EM900 before and after infection also reduced the mRNA and protein expression of intercellular adhesion molecule-1 (ICAM-1), which is the receptor for RV14, after infection and reduced the activation of the nuclear factor kappa-B protein p50 in nuclear extracts after infection." (PMID 26462747, 2015). "For example, donor 23 cells were less infected by RV-A16 at 24 hrs, despite having similar levels of ICAM1 gene expression compared to other non-asthmatic donor cells before and after RV-A16 infection." (PMID 25706956, 2015). "Based on our findings, we hypothesize that infection with PbA opens the BBB, which leads to the recruitment of numerous activated CD8+ T cells, ICAM-1+ macrophages, and neutrophils." (PMID 25474413, 2014). "The modulatory effect of anti-ICAM-1 antibody enhances the migratory capacity of neutrophils to the infection locus while attenuating its infiltration to nonspecific organs." (PMID 24891762, 2014). "In contrast, our cell culture model of PHH revealed that ICAM-1 mRNA expression in hepatocytes is increased already 2 h after infection with H. hepaticus, without additional stimulation of acute phase cytokines by bystanding immunological cells." (PMID 24932686, 2014). "The difference in disease outcome between the two groups could then be attributable to the degree of ICAM-1 expression in the presence of parasite expressing ICAM-1 binding VSA and/or other factors aside just infection with ICAM-binding parasites." (PMID 24386348, 2013).
infection (continued). "The release of IL-1β and IL-8 (data not shown), were inhibited in the presence of the anti-ICAM-1 antibody showing that infection of NHBE cells by HRV14 was required to trigger a measurable cytokine release." (PMID 23723976, 2013). "Therefore, cell culture supernatants collected at 24 h post infection were analyzed for the presence of MCP-1, IL-8, IL-6, GM-CSF, and soluble cell adhesion molecules (ICAM-1, VCAM-1, and E-selectin)." (PMID 24069284, 2013). "In addition, when both ICAM-1 and LFA-1 were simultaneously blocked, inhibition of mDC-mediated trans-infection of HIV-1 to primary CD4+ T cells reached 75% to 90% in both autologous and allogeneic co-cultures (p < 0.05)." (PMID 23590845, 2013). "HRV serotypes are principally major or minor group viruses which bind to intracellular adhesion molecule-1 (ICAM-1) or low-density lipoprotein (LDL) receptor respectively, and there is also a group of HRV-C viruses for which the mode of infection is unknown." (PMID 23723976, 2013). "Plasmodium knowlesi infected erythrocytes from human infections bind in a specific but variable manner to the human endothelial cell receptors ICAM-1 and VCAM but not to CD36." (PMID 22305466, 2012). "The nearly equal specific infectivity of ICAM+ and ICAM− viruses in TZM-bl cells shows that incorporation of ICAM-1 does not compromise the virus' ability to establish productive infection." (PMID 22970312, 2012). "As ICAM-1 is located at the apical surface of polarized epithelial cells, these results strongly suggest LFA-1 and ICAM-1 play no role in transfer infection of polarized epithelial cells in vivo." (PMID 21573183, 2011). "In contrast to transfer infection of non-polarized cells, infection via the basolateral surface was unaffected by the presence of blocking antibodies to LFA-1 or ICAM-1." (PMID 21573183, 2011). "No inhibition of the surface protein ICAM-1 was observed on the Jurkat T-cells following VSV10 infection (data not shown)." (PMID 21857986, 2011). "As expected, for ICAM-1 tropic HRVs and CVA21, receptor blocking led to a >90% decrease of infection, whereas minor group HRVs and CVB3, which use the low density lipoprotein (LDL)-receptor or coxsackievirus adenovirus receptor (CAR), respectively, were not affected." (PMID 20937137, 2010). "In the current study, although genetic deletion of IP-10 substantially reduced systemic IFN-γ levels, it did not affect ICAM-1 expression on the brain microvasculature during infection." (PMID 19343215, 2009). "Many parasite isolates from children adhere to ICAM-1, and adults frequently have antibodies to VSA expressed by such isolates, so host immunity may prevent them from establishing infection in pregnant women." (PMID 18364051, 2008). "The present data show that IFN-γ induces phosphorylation of STAT-1; its effects on membranous ICAM-1 levels are inhibited in a dose-dependent fashion by AG490 in the absence of infection." (PMID 18534017, 2008). "The secondary role of ICAM-1 in HIV transfer between CD4 T cells and its limited effect in 293T cells is contradictory with the more relevant role reported in the infection of CD4 T cells by free HIV particles, and the complete requirement of this molecule for transinfection induced by DC." (PMID 18377648, 2008). "TNF may then activate endothelial cells by promoting the expression of adhesion molecules like intercellular adhesion molecule 1 (ICAM-1), vascular cell adhesion molecule 1 (VCAM-1), and the secretion of chemokines that attract immune cells to the site of infection." (PMID 40283058, 2025). "However, it is unknown whether ICAM-1 and LDL1 receptors also mediate the infection in vivo, i.e., in the nasal tissue, with rhinoviruses." (PMID 38473734, 2024). "Importantly, ICAM-1 mRNA and proteins levels were unaffected by HRV16 infection." (PMID 39324790, 2024).